ACE (angiotensin I converting enzyme)
Diseases named in the same sentence as ACE in open-access papers (continued):
Sharing a sentence is not in itself a finding about the gene and the disease.
ischemic stroke (continued). "Therefore, we present herein the results of a large meta-analysis of published data investigating the association between ACE I/D and ischemic stroke for various genetic contrasts, in which we explored the between-studies heterogeneity and the existence of potential bias." (PMID 23049705, 2012). "In the acute phase of ischemic stroke, overactivation of the angiotensin-converting-enzyme (ACE)/angiotensin (Ang II)/angiotensin receptor 1 (AT1R) axis, sympathetic and baroreceptor dysregulation are frequently observed." (PMID 36768443, 2023). "All of the miRNAs included in our study, miR-10a, miR-27a, miR-34b/c, and miR-300, were predicted to target either PAI-1 or ACE mRNA, based on previous miRNA studies performed for ischemic stroke." (PMID 33255549, 2020). "ACE is associated with the thrombosis pathway, and several studies have demonstrated associations between ACE and PAI-1 and between ACE and ischemic stroke." (PMID 33255549, 2020). "Specifically, blocking angiotensin-converting enzyme (ACE) or AT-1 receptors has been demonstrated to be neuroprotective following ischemic stroke in experimental animals and humans." (PMID 31551909, 2019). "ACE is involved in the Renin-Angiotensin-Aldosterone system and implicated in microvascular complications in Diabetes III (MVCD3) and ischemic strokes." (PMID 28553317, 2017). "Considering that the type of Ang II receptors involved in mediation of ACE expression after ischemic stroke has rarely been demonstrated before, we investigated which type of Ang II receptors are involved in ACE activation in our study." (PMID 29228591, 2017). "The deleterious effects of brain Angiotensin-converting enzyme (ACE) - Angiotensin II (Ang II) - Angiotensin II type 1 receptor (AT1R) axis in the pathogenesis of ischemic stroke were well elucidated by several studies." (PMID 23997755, 2013). "Many studies have investigated the association between the angiotensin-converting enzyme (ACE) gene insertion/deletion (I/D) polymorphism and risk of ischemic stroke." (PMID 23049705, 2012). "Besides ACE2 downregulation, the interrupted balance in the demand of ACE and angiotensin II with an increment of proinflammatory disposition and endothelial damage contributes to the pathogenesis of ischemic stroke." (PMID 35328506, 2022). "With regard to the ACE D/I polymorphism, only migraineurs with aura carrying the DD/DI genotype seemed to be at increased risk for ischemic stroke and MI, but not carriers of the II genotype." (PMID 21779381, 2011). "Additional studies, such as replication studies, are necessary to confirm whether any miRNA polymorphisms play crucial roles in ischemic stroke pathogenesis and to provide further evidence regarding whether the regulation of PAI-1 and ACE expression can be used to prevent ischemic strokes." (PMID 33255549, 2020). "Polymorphisms affecting various genes, such as angiotensin converting enzyme (ACE), thrombin-activatable fibrinolysis inhibitor (TAFI), and nitric oxide synthase (NOS) genes, as suggested by recent advances in genetic research techniques are associated with the incidence of ischemic stroke." (PMID 30997974, 2019). "Thus, the ACE gene is a good candidate gene for ischemic stroke." (PMID 23049705, 2012). "In COVID-19-mediated ischemic stroke, where the protective effects of ACE2 are downregulated or depleted due to the interaction between S protein and SARS-CoV-2, the balance is tilted in favor of ACE and angiotensin II." (PMID 35328506, 2022). "Several studies reported that regulation of the RAS by ACE inhibitors and ARBs has a cerebral protective effect against ischemic stroke independent of a hypotensive effect, whereas non-RAS antihypertensive agents such as hydralazine and nimodipine have not shown cerebral protection." (PMID 32922259, 2020).
pulmonary hypertension (44 papers, 2005 to 2025). Increased pressure within the pulmonary circulation due to lung or heart disorder. "The association between ACE DD genotype and pulmonary hypertension during exercise in COPD patients has been reported." (PMID 32042834, 2019). "The relationships between ACE polymorphism and autism, the pathogenesis of pulmonary hypertension, psoriasis, chronic kidney failure, and so on have been reported." (PMID 27830153, 2016). "According to a meta-analysis, ACE gene polymorphisms, particularly the D/D genotype, may increase the risk of respiratory disease with pulmonary hypertension." (PMID 36644496, 2023). "Furthermore, an association between an ACE I/D polymorphism (the D allele of the human ACE gene confers increased ACE activity in plasma), and pulmonary hypertension has been reported; this association is, however, controversial." (PMID 34441050, 2021). "The DD genotype of the angiotensin-converting enzyme (ACE) is associated with pulmonary hypertension and tissue oxygenation with exercise, raising questions as to whether it is associated with the phenotype of COPD." (PMID 24724085, 2014). "Interestingly, the ACE DD genotype, associated with an increased myocardial ACE activity, is more frequent in patients with pulmonary hypertension than in healthy individuals, but it is also associated with preserved RV function in pulmonary hypertension patients." (PMID 30618811, 2018). "For instance, the increased expression of angiotensin converting enzyme (ACE) along with angiotensin II (Ang II) was observed in the development of pulmonary hypertension (PH)." (PMID 27724864, 2016). "Furthermore, BIOiSIM was an ML-based simulation program for pulmonary hypertension remedies with Angiotensin-Converting Enzyme (ACE) and calcium channel blockers (CCB) aimed at repurposing and new drug discovery for SARS-CoV-2." (PMID 41283338, 2025). "Compared to normal hearts, however, angiotensin II binding is diminished in the failing RV of pulmonary artery hypertension patients due to angiotensin II type 1 receptor down-regulation, despite RV myocardial angiotensin converting enzyme (ACE) activity being increased." (PMID 30618811, 2018). "In this study, as in studies in pulmonary hypertension, DIZE treatment was associated with reduced tissue ACE activity, which is likely to be an indirect effect due to an improvement in tissue injury and therefore less ACE activation." (PMID 25786223, 2015). "Furthermore, ACE2 works in opposition to ACE and may lead to vasodilation from vasoconstriction, either locally or throughout the lung, to ameliorate pulmonary hypertension due to poor angiogenesis." (PMID 36405683, 2022). "In addition to participation of metabolic and cytokine gene in COPD development, ACE (Angiotensin-Converting Enzyme) gene was also suggested as essential factor responsible for the progression of pulmonary hypertension which may leads to COPD." (PMID 32042834, 2019). "The activation of this pathway provides a shield against the adverse effects mediated by RAS or by the ACE/AngII/AT1R axis, such as lung inflammation, fibrosis, pulmonary arterial hypertension, and alveolar epithelial cell apoptosis." (PMID 39195662, 2024). "Although the D allele is linked to increase of plasma ACE activity in COPD, the D allele has not been associated with pulmonary hypertension or COPD, which is in accordance with our results." (PMID 36819141, 2023). "Currently, some studies have linked MIF concentration to particular SSc presentations, such as pulmonary arterial hypertension (PAH), impaired lung function, and ACE inhibitor usage, although not all studies have confirmed this." (PMID 38790215, 2024). "Recently, it was shown that animal models of PAH, hypoxic pulmonary hypertension (HPH) and human patients with PAH, including idiopathic pulmonary arterial hypertension (IPAH), might have an increased ratio of ACE/ACE2." (PMID 34884604, 2021).
Myocardial fibrosis (41 papers, 2011 to 2025). "The ACE gene DD genotype is linked to higher cellular ACE activity, leading to myocardial fibrosis." (PMID 23170137, 2012). "Although the mechanisms/pathways by which ACE inhibitors affect myocardial fibrosis are complex, angiotensin II was shown to stimulate fibroblast proliferation and ECM synthesis through the TGF-β pathway— a key regulator of collagen synthesis." (PMID 39301014, 2024). "In a study using a small number of patients with hypertensive heart disease, ACE inhibition with lisinopril regressed myocardial fibrosis on endomyocardial biopsy that was accompanied by improved LV diastolic function." (PMID 35600469, 2022). "Chymotrypsin can receive the signal of angiotensin converting enzyme (ACE), produce angiotensin II and activate MMPs, so as to promote myocardial fibrosis and cardiac remodeling." (PMID 36120366, 2022). "To evaluate potential factors contributing to LV dilation and myocardial fibrosis, we assessed ACE activity in kidney, lung and LV tissue samples from Dmdmdx and wt rats at 9 months of age." (PMID 33619211, 2021). "Angiotensin II (AngII), which is subsequently cleaved from angiotensin I by angiotensin I converting enzyme (ACE), can activate multiple cardiovascular processes and lead to cardiomyocyte hypertrophy, ventricular remodeling, and myocardial fibrosis." (PMID 27843475, 2016). "ACE2 is a counter-regulatory homologue of angiotensin-converting enzyme (ACE) and a major regulator of endothelial function and myocardial fibrosis." (PMID 24923671, 2014). "Even though this mechanism has been seen in other causes of myocardial fibrosis, the role of ACE inhibitors in RHD cases has not yet been confirmed." (PMID 37564912, 2023). "Angiotensin-converting enzyme (ACE) inhibitors might confer survival benefits in AS by regulating left ventricular remodeling and myocardial fibrosis." (PMID 36312243, 2022). "Accordingly, a recent randomized clinical trial has demonstrated that drugs inhibiting the RAAS, including ACE inhibitors, significantly reduce the progression of myocardial fibrosis in patients with DMD or BMD, suggesting a deleterious role of ACE in DMD-related myocardial fibrosis." (PMID 33619211, 2021). "ACE inhibitor treatment improves morbidity and mortality in post-MI patients, and related studies have shown that perindopril can delay myocardial remodeling and myocardial fibrosis." (PMID 34257682, 2021). "In the current study, elevated ACE activity in hypertensive heart may enhance the conversion of angiotensin I (Ang I) into bioactive angiotensin II (Ang II) which clearly mirrors the part of Ang II in myocardial fibrosis." (PMID 25531679, 2014). "ACE-inhibitors are considered to be potentially beneficial, especially for RHD, not only in interfering with the RAA system but also for attenuating myocardial fibrosis by inhibiting TGF-β signaling." (PMID 37564912, 2023). "Of note, angiotensin-converting enzyme (ACE) inhibitors and angiotensin receptor blockers (ARB) were shown to reduce the development of myocardial fibrosis and hypertrophy, as well as LV adverse remodeling, hence reducing the onset of HF." (PMID 35972638, 2022). "Based on these reports, it is essential to achieve optimal medical therapy with an ACE inhibitor (or ARB) and a beta blocker, especially for patients with HF and myocardial fibrosis." (PMID 26892530, 2016). "ACE inhibitors reduce inflammation and fibrosis by lowering IL-6 and TNF-α, and also trigger the apoptosis of cardiac fibroblasts, which generate pathological ECM components for myocardial fibrosis." (PMID 37564912, 2023). "In the present OSA-model, both ACE upregulation and MMP-2 downregulation could promote myocardial fibrosis." (PMID 24775918, 2014). "Various studies have shown that both angiotensin-converting enzyme (ACE) inhibitors and angiotensin II receptor blockers (ARBs) significantly reduce myocardial fibrosis regardless of their hypotensive effect." (PMID 36221014, 2023).
pulmonary fibrosis (40 papers, 2004 to 2025). Chronic progressive interstitial lung disorder characterized by the replacement of the lung tissue by connective tissue, leading to progressive dyspnea, respiratory failure, or right heart failure. "These mutations can lead to an increase in ACE activity, contributing to pulmonary inflammation and promoting lung fibrosis." (PMID 40800134, 2025). "Surprisingly, we subsequently identify a protective role for AcPGP in limiting pulmonary fibrosis, and we demonstrate the pathogenic function attributed to ACE in fibrosis to be a consequence of overzealous AcPGP degradation." (PMID 29202450, 2017). "RAS dysregulation has been implicated in pulmonary fibrosis onset, in particular due to the downstream actions of angiotensin I (Ang I), which is cleaved by ACE into angiotensin II (Ang II); Ang II promotes inflammatory and fibrotic responses through the receptor (AT1R)." (PMID 35308222, 2022). "Mice deficient in the N-domain of ACE were protected from bleomycin-induced lung fibrosis." (PMID 29202450, 2017). "Consequently, we identify a potentially novel protective role for AcPGP in limiting pulmonary fibrosis and suggest the pathogenic function attributed to ACE in idiopathic pulmonary fibrosis (IPF) to be a consequence of overzealous AcPGP degradation." (PMID 29202450, 2017). "N-terminal truncation mutations of ACE in mice demonstrate protection from bleomycin-induced lung fibrosis and such anti-fibrotic effects phenotype in N-terminal truncation mutant mice was abolished when treated with S-17092, a prolyl-oligopeptidase inhibitor that inhibits the formation of AcSDKP37." (PMID 27425816, 2016). "Furthermore, activation and production of AngII is associated with lung fibrosis which can be attenuated by AT1 blocker or ACE inhibitor." (PMID 22802960, 2012). "Therefore, the interplay between the ACE2/ACE and the Rho GTPase pathway may be an important association that could be a target for therapeutics to block lung fibrosis that results in ARDS and a majority of the mortality in COVID-19 patients." (PMID 32991251, 2020). "In addition, it is predicted that inheritance of this variant with the arginine/arginine genotype in codon 25 of TGF-β1 and/or the D allele of ACE, which also has been associated with more severe lung fibrosis, will further intensify the progression or severity of IPF." (PMID 22500179, 2012). "Angiotensin-converting enzyme (ACE) inhibitors have shown efficacy for the treatment of pulmonary fibrosis in pre-clinical models." (PMID 40832404, 2025). "The results showed an image of the heart and lung regions indicating the targeting of an angiotensin-converting enzyme (ACE), which was overexpressed in cardiac and pulmonary fibrosis." (PMID 35455438, 2022). "A recent post hoc analysis of data from the placebo arms of phase 3 trials including patients with idiopathic pulmonary fibrosis, showed a slower disease progression in patients under therapy with ACE inhibitors." (PMID 32503281, 2020). "The ACE2 cascade is protective against lung fibrosis through activation of Rho GTPase pathways, while ACE is damaging and stimulates fibrosis in lung endothelial cells." (PMID 32991251, 2020). "Concurringly, findings from a substantial number of in vivo studies demonstrated that ACE inhibitors were capable of attenuating experimental pulmonary fibrosis." (PMID 32503281, 2020). "Angiotensin converting enzyme (ACE) and Ang II are associated with tissue remodeling in fibrotic diseases such as cardiovascular fibrosis and pulmonary fibrosis." (PMID 30669315, 2019). "The role of AngII in pulmonary fibrosis is evidenced by studies that show ACE inhibitors or AT1R-selective antagonists attenuate experimental pulmonary fibrosis." (PMID 29075197, 2017).
pulmonary fibrosis (continued). "In summary, these studies suggest that MDK plays an important regulatory role in the pathogenesis of lung fibrosis, including promoting inflammation and extracellular matrix deposition, participating in epithelial-mesenchymal transition, and modulating ACE expression." (PMID 38075691, 2023). "This indicates that MDK may promote lung fibrosis by interacting with Notch2 and activating angiotensin-converting enzyme (ACE) expression." (PMID 38075691, 2023). "ARBs and neprilysin inhibitors (Valsartan and Sacubitril) reduced fibrosis, pulmonary pressures, vascular remodeling, as well as right-ventricle hypertrophy in a rat model, while both ARBs and ACE-Is have been shown to possess a modulating effect in idiopathic pulmonary fibrosis." (PMID 37509613, 2023). "Furthermore, we demonstrated that the capacity of the ACE inhibitor, captopril, to ameliorate bleomycin-induced pulmonary fibrosis was entirely dependent on AcPGP accumulation, since protection was abolished by the AcPGP antagonist RTR." (PMID 29202450, 2017). "Previous studies have demonstrated that the occurrence and progression of pulmonary fibrosis are facilitated by an increase in local angiotensin Ang-II within lung tissue during acute respiratory distress syndrome, which exerts its effects through the ACE/Ang-II/AT1R pathway." (PMID 40160824, 2025). "A previous study of thoracic irradiation in rats demonstrated that treatment with captopril, enalapril (another ACE inhibitor) and an angiotensin receptor blocker (L 158,809) was sufficient to block the production of TGF-β1, a primary cytokine implicated in the development of pulmonary fibrosis." (PMID 33616187, 2021). "Angiotensin II upregulates the expression of profibrotic cytokines leading to pulmonary fibrosis and severe inflammation with increased vascular permeability, a scenario that may be attenuated by angiotensinogen converting enzyme (ACE) inhibitors and angiotensin receptor blocker (ARB) therapies." (PMID 32838280, 2020). "The angiotensin-converting enzyme (ACE) test showed 7 U/L (reference: 9–67 U/L) and chest radiography revealed mild pulmonary fibrosis." (PMID 40260189, 2025). "Treatment with ACE inhibitors and angiotensin type 1 receptor (AT1) antagonists mitigates pneumonitis and lung fibrosis in animal models induced by bleomycin and by thoracic irradiation." (PMID 33616187, 2021). "ACE and ANG II have been proposed to be involved in fibrotic diseases, such as cardiovascular fibrosis and pulmonary fibrosis." (PMID 27261452, 2016). "ACE and ANG II are involved in fibrotic diseases, such as cardiovascular fibrosis and pulmonary fibrosis." (PMID 27261452, 2016). "Furthermore, suppressing the ACE/Ang II/AT1R pathway using acetyl-seryl-asparyl-lysyl-proline, an anti-fibrotic peptide, reduces EMT and abnormal ECM deposition in silica-induced pulmonary interstitial fibrosis." (PMID 40800134, 2025). "Ang II is hydrolyzed from Ang I under the action of ACE, and the binding of Ang II with AT1 may be involved in the process of pulmonary fibrosis as a pro-fibrosis mediating factor." (PMID 35685407, 2022). "Concerning the correlation of lung fibrosis with RAS, hyperoxia increases the collagen and α-smooth muscle actin (α-SMA) expression via RAS components including angiotensinogen and ACE, and angiotensin II expression is also significantly increased by hyperoxic exposure in human lung fibroblasts." (PMID 23762250, 2013). "Likewise, inhibitors of chymase, one of the other enzymes known to have the same ability as ACE to convert ANGI to ANGII, have been shown to inhibit paraquat-induced lung injury and fibrosis in mice and bleomycin-induced lung fibrosis in hamsters." (PMID 22500179, 2012). "Moreover, ACE inhibitors and non-selective Ang II receptor antagonists, such as saralasin, effectively block experimental lung fibrosis in animal models." (PMID 40800134, 2025).
pulmonary fibrosis (continued). "All major components of the RAS exhibit profibrotic activity, such as Angiotensin converting enzyme (ACE) and angiotensinogen may contribute to increased Ang II production, and Ang II plays important roles in the development of renal, hepatic, as well as pulmonary fibrosis." (PMID 35685407, 2022).